LNCARGI (lncRNA antiviral response interferon signaling inducer)
Synonyms: ARGI
Gene: Long non-coding RNA gene on chromosome 13 (99,429,211 to 99,432,702, reverse strand). Ensembl gene ENSG00000285448.
Diseases named in the same sentence as LNCARGI in open-access papers:
LNCARGI is named in the same sentence as 28 diseases in open-access papers, as found by Europe PMC text mining. Sharing a sentence is not in itself a finding about the gene and the disease.
LNCARGI shares sentences with these, for which no sentence is quoted: tumor (17 papers); infection (6); atherosclerosis (4); Hyperammonemia (3); lung carcinoma (3); breast carcinoma (2); cancer (2); COVID-19 (2); diabetes (2); endothelial dysfunction (2); melanoma (2); non-small cell lung carcinoma (2); viral infection (2); asthma (1); autoimmune myocarditis (1); breast tumor (1); cervical cancer (1); chronic cystitis (1); chronic obstructive pulmonary disease (1); cystic fibrosis (1); enteroviral infections (1); Hypertension (1); liver diseases (1); liver steatosis (1); Obesity (1); pulmonary hypertension (1); Stroke (1); type 2 diabetes mellitus (1).